STAT6 (signal transducer and activator of transcription 6)
Diseases named in the same sentence as STAT6 in open-access papers (continued):
Sharing a sentence is not in itself a finding about the gene and the disease.
hepatic disease (2 papers, 2011 to 2025). "In consequence, STAT6 could represent an interesting therapeutic target, notably in the field of liver disorders." (PMID 41409600, 2025).
Hypertension (2 papers, 2013 to 2019). The presence of chronic increased pressure in the systemic arterial system. "P-PIC TLR3 KO mice did not develop hypertension and placental HIF-1α, NF-κBp50, miR-210, STAT6, and IL-4 levels were unchanged." (PMID 23844087, 2013).
ischemia (2 papers, 2022 to 2023). A hypoperfusion of the BLOOD through an organ or tissue caused by a PATHOLOGIC CONSTRICTION or obstruction of its BLOOD VESSELS, or an absence of BLOOD CIRCULATION. "Interleukin 4 receptor alpha chain (IL-4Ra) is expressed in neurons and plays a critical role in modulating neuronal death through activation of signal transducer and activator of transcription 6 (STAT6) during ischemia." (PMID 36782269, 2023).
ischemia reperfusion injury (2 papers, 2020 to 2021). Adverse functional, metabolic, or structural changes in ischemic tissues resulting from the restoration of blood flow to the tissue (reperfusion), including swelling; hemorrhage; necrosis; and damage from free radicals. "Notably, a protective or reparative role of STAT6 was also observed in the kidney following ischemia-reperfusion injury or diphtheria toxin-induced AKI." (PMID 33511217, 2021).
keloid (2 papers, 2023 to 2025). An irregularly shaped, elevated mark on the skin caused by deposits of excessive amounts of collagen during wound healing. "We found that JAK/STAT6 signaling, which is known to induce M2 polarization, was activated in keloid tissues and KFs." (PMID 36757802, 2023). "We established a keloid implantation model in BALB/c nude mice using fresh keloid tissues to assess the effect of p-STAT6 inhibition on keloid progression in vivo." (PMID 36757802, 2023). "Ectopic expression of IL-13RA2 in keloid fibroblasts resulted in inhibition of STAT6 phosphorylation, cell proliferation, migration, invasion, extracellular matrix secretion, and myofibroblast marker expression, as well as an increase in apoptosis." (PMID 36757802, 2023). "In the present study, we have found that IL-13 signaling and the downstream JAK/STAT6 pathway are activated by the downregulation of IL-13RA2 in keloids." (PMID 36757802, 2023). "Tissue protein lysates from both keloids and normal dermis were assayed by Western blotting, and p-STAT6 was found to be upregulated in keloids." (PMID 36757802, 2023). "Inhibiting the phosphorylation of STAT6 and ectopic overexpression of IL-13RA2 alleviate keloid fibrogenesis by inducing apoptosis and suppressing the migration, invasion, and collagen synthesis of myofibroblasts in vitro and in vivo." (PMID 36757802, 2023). "We therefore examined the level of p-STAT6 in keloid tissues and healthy skins." (PMID 36757802, 2023). "IHC staining of p-STAT6 also showed a significantly elevated expression in keloid reticular dermis." (PMID 36757802, 2023). "Knockdown of IL13RA2 in NFs induced keloid-characteristic behaviors via JAK/STAT6 signaling." (PMID 36757802, 2023). "Furthermore, Western blot assay of NFs and NFs with Pearson’s correlation test of gray values revealed a negative correlation between IL-13RA2 expression and the p-STAT6/STAT6 ratio, suggesting an important role of IL-13RA2 in JAK/STAT6 activation in keloids." (PMID 36757802, 2023). "Thus, we speculate that myofibroblast adipogenesis may be inhibited, at least in part, due to JAK/STAT6 activation in keloids, resulting in excess scar formation, which requires further investigation." (PMID 36757802, 2023). "Furthermore, both in vitro application and intratumoral injection of p-STAT6 inhibitor AS1517499 in a patient-derived xenograft keloid-implantation mouse model resulted in proliferation inhibition and tissue necrosis, apoptosis, and myofibroblast marker reduction." (PMID 36757802, 2023). "In keloids, the pro-proliferative effects occur via the decoy effect of IL13RA2 and reduced IL13RA2 leads to accelerated IL13-induced fibrosis through STAT6." (PMID 40663259, 2025). "Collectively, this study elucidates the key role of IL-13RA2 in keloid pathology and inspires further translational research of keloid treatment concerning JAK/STAT6 inhibition." (PMID 36757802, 2023). "Western blotting revealed that the level of phosphorylated STAT6 (p-STAT6), a known inducer of M2 polarization, was higher in keloid fibroblasts as opposed to fibroblasts from normal dermis." (PMID 36757802, 2023). "Finally, we chose AS1517499 to inhibit JAK/STAT6 in the patient-derived xenograft (PDX) model instead of directly regulating IL-13RA2 expression because there is still a lack of established animal models of keloids, and we believe organoid cultures and PDX will bridge current difficulties." (PMID 36757802, 2023).
leprosy (2 papers, 2019 to 2024). Leprosy is a chronic infectious disease affecting primarily the skin and peripheral nervous system. "In the present study, we studied the effect of M. leprae antigens on transcription factors STAT-4, STAT-6 and CREB and their correlation with Th1/Th2 cell mediated immune responses in leprosy." (PMID 30642265, 2019). "This study shows differential expression of T cell transcription factor STAT-4, STAT-6 and CREB in leprosy patients and healthy individuals correlating with Th1 and Th2 cytokine expression." (PMID 30642265, 2019). "This study has been done to correlate differential Th1/Th2 cell mediated immune responses observed in leprosy with known T cell transcription factors (STAT-4, STAT-6 and CREB) ex vivo along with the effect of M. leprae antigens (MLSA, WCL and PGL-1) on the modulation of these transcription factors." (PMID 30642265, 2019). "Therefore, in the present study we have studied M. leprae antigens mediated Th1/Th2 specific T cell transcription factors STAT-4, STAT-6, and CREB activation and cytokine production in leprosy patients and healthy individuals." (PMID 30642265, 2019).
lupus nephritis (2 papers, 2021 to 2026). Glomerulonephritis in the context of systemic lupus erythematosus. "Thus, for the first time, we demonstrated that TGP may be a potent drug to treat lupus nephritis by inducing F4/80+CD11b+CD206+ and F4/80+CD11b+PD-L2+ macrophages through IL-4/STAT6/PD-L2 signaling pathway." (PMID 34290705, 2021).
malignant glioma (2 papers, 2017 to 2019). A grade III or grade IV glioma arising from the central nervous system. "Here we show that STAT6 is epigenetically silenced in some cases of malignant glioma, ultimately preventing cancer cell death by inducing HIF-1α expression via the mTOR-S6K-S6 pathway." (PMID 31530290, 2019). "It is known that miR-135a can function as a selective killer of malignant glioma by targeting STAT6, SMAD5 and BMPR2." (PMID 28415713, 2017). "Further, in malignant glioma cells, it has shown that IL-4 induces aberrant STAT3 activation, but not STAT6 activation, suggesting that a defective STAT6 signal might drive STAT3 activation." (PMID 31530290, 2019).
mesothelioma (2 papers, 2016 to 2025). A usually malignant and aggressive neoplasm of the mesothelium which is often associated with exposure to asbestos. "(d) NAB2-STAT6 gene fusion in (NAB2 exons 1–6, STAT6 exons 17–22) present in TCGA SH A7BH, originally diagnosed mesothelioma." (PMID 40875449, 2025). "We used Arriba to confirm that SH-A7BH was, in fact, the only tumor in the mesothelioma cohort containing a NAB2-STAT6 fusion (exons 1–6 of NAB2 and 16–22 of STAT6)." (PMID 40875449, 2025). "In the immunohistochemical evaluation of STAT6 expression and subcellular localization, these excluded mimics and two additional cases of each pulmonary sarcomatoid carcinoma and mesothelioma were used as the negative controls." (PMID 26686340, 2016).
myocarditis (2 papers, 2023 to 2025). Myocarditis is a condition that is characterized by inflammation of the heart muscle (myocardium). "In mice, while IL-4 plays a critical role in controlling myocarditis and inhibiting Th1 cell responses that produce IFN-γ, it is also implicated in intracellular parasite replication and, notably, in the phosphorylation of STAT6 in cardiac fibroblasts, leading to increased collagen production." (PMID 40391216, 2025).
pemphigus vulgaris (2 papers, 2020 to 2022). Pemphigus is a group of chronic autoimmune skin diseases characterized by blister formations on the outer layer of the skin and the mucous membranes. "That is why the aim of this study was to evaluate the expression of proteins JAK3, STAT2, STAT4, and STAT6 in skin lesions and perilesional area in patients with pemphigus vulgaris as well as in the control group." (PMID 32170648, 2020). "The aim of this study was to evaluate the expression of proteins: JAK3, STAT2, STAT4 and STAT6 in epithelium lesions in patients with pemphigus vulgaris (PV), bullous pemphigoid (BP), oral lichen planus (LP) and chronic ulcerative stomatitis (CUS), as well as in the control group." (PMID 36613766, 2022).
Peritoneal Fibrosis (2 papers, 2022 to 2023). Disorder characterized by a wide range of structural changes in PERITONEUM, resulting from fibrogenic or inflammatory processes. "Our study showed that TA suppressed the expression of STAT6 in CG-induced peritoneal fibrosis and injured Raw264.7 cells." (PMID 35784347, 2022). "We demonstrated that HDAC8 promoted the EMT of HPMCs via EGFR/ERK1/2/STAT3/HIF-1α, induced M2 macrophage polarization via STAT6 and PI3K/Akt signaling pathways, and ultimately accelerated the process of peritoneal fibrosis." (PMID 36911746, 2023).
peritonitis (2 papers, 2021 to 2022). Inflammation of the peritoneum (tissue that lines the abdominal wall and covers most of the organs in the abdomen). "We further evaluated the effects of pharmacologic inhibition of STAT6 phosphorylation on the efferocytic ability of macrophages during zymosan-induced acute peritonitis." (PMID 35327639, 2022). "STAT6 has been shown to be a key player in protecting against lethal endotoxemia and zymosan-induced peritonitis." (PMID 35327639, 2022). "First, we characterized STAT6 activation in peritoneal macrophage and spleen samples during zymosan-induced acute peritonitis." (PMID 33652833, 2021). "The goal of our study was to determine the role of STAT6 in PPARγ activation to resolve acute sterile inflammation in a zymosan-induced peritonitis murine model, which has been widely used as a self-resolving model of acute inflammation." (PMID 33652833, 2021). "Here, we studied the role of STAT6 signaling in PPARγ activation and the resolution of acute sterile inflammation in a murine model of zymosan-induced peritonitis." (PMID 33652833, 2021). "Here, in a model of zymosan-induced peritonitis, we demonstrated the critical role of STAT6 activation in the recovery and enhancement of PPARγ expression and activation in peritoneal macrophages." (PMID 33652833, 2021). "Our results indicate that specifically targeting the STAT6/PPARγ signaling pathway might be a novel therapeutic approach for treating sterile inflammatory diseases, including peritonitis." (PMID 35327639, 2022). "In the present study, we examined whether inhibition of STAT6 phosphorylation by AS1517499, a STAT6-specific pharmacological inhibitor, affects PPARγ expression and activation during zymosan-induced peritonitis." (PMID 35327639, 2022). "Thus, we examined the role of STAT6 in changing the efferocytic ability of peritoneal macrophages during zymosan-induced acute peritonitis." (PMID 33652833, 2021). "Previous studies suggest that IL-4 and IL-13, two cytokines known to induce STAT6 activation, are not involved in STAT6 phosphorylation during zymosan-induced peritonitis." (PMID 35327639, 2022). "Thus, in the present study, we investigated whether modulating STAT6 activity using a selective STAT6 inhibitor, AS1517499, influences the inflammatory response in zymosan-induced peritonitis by regulating PPARγ expression and activity." (PMID 35327639, 2022). "However, in the present study, we found that, similar to IL-4 and IL-13, the TSG6 mRNA and/or protein levels remained the same in PLF, peritoneal macrophages, and spleen after zymosan injection, indicating that TSG6 is not involved in the STAT6 pathway during zymosan-induced peritonitis." (PMID 35327639, 2022).
Pituitary Adenomas (2 papers, 2022 to 2025). "Additional genes—PHYHD1, LTBR, MYBPHL, C22orf42, PRR5, ANKDD1A, RAB13, CAMKV, KIFC3, WNT4, and STAT6—were implicated in the invasive behavior of non-functioning pituitary adenomas (NFPAs)." (PMID 39859246, 2025).
polycystic kidneys (2 papers, 2016 to 2024). "We and others have shown that PC1-p30 is overexpressed in polycystic kidneys, targets to the nucleus and regulates the activities of several transcription factors including STAT3, STAT6, TCF and CHOP." (PMID 27560828, 2016).
respiratory infection (2 papers, 2021 to 2024). "STAT6 also promotes respiratory infection caused by Ch. pneumoniae and further enhanced its downstream process." (PMID 34226412, 2021). "In addition, it was observed that STAT6 also promotes respiratory infection caused by Ch. pneumoniae and further enhanced the downstream process." (PMID 34226412, 2021). "There was a significant decrease in only two inflammatory mediators, PTGS2 and Stat6, in response to the respiratory infection, with no changes to any other mediator observed." (PMID 38879567, 2024).
SARS-CoV infection (2 papers, 2014 to 2025). "A role for AAM differentiation in immune-pathology has been elegantly verified in SARS-CoV infection using STAT6- and STAT1-deficient animals." (PMID 40854598, 2025).
squamous carcinoma (2 papers, 2019 to 2022). "In human LUAC squamous cell carcinoma, high expression of STAT6 has been detected." (PMID 35600336, 2022). "Significantly higher STAT6 immunoexpression level was observed in all histopathological non-small-cell lung cancer (NSCLC) subtypes (squamous cell carcinoma, adenocarcinoma, and large-cell carcinoma), especially higher expression found in squamous cell carcinoma than in large-cell carcinoma." (PMID 31798581, 2019).
thyroid tumor (2 papers, 2024 to 2025). A benign or malignant neoplasm affecting the thyroid gland. "This reveals the potential role of the TGF-β-SMA4 signaling pathway in the malignancy-associated modulation of TIME and stimulates further discovery of the diagnostic and prognostic role of STAT6 and SMAD4 in thyroid tumors." (PMID 39936166, 2025). "Moreover, p-STAT6 was found to be higher in thyroid tumor cells compared with normal thyrocytes indicating that the STAT6 pathway is constitutively activated in thyroid tumor cells." (PMID 38773979, 2024). "Our results demonstrate that STAT6 and SMAD4 molecules are interconnected with the number of certain classes of immune cells, and therefore may play a role in the regulation of the immune microenvironment of thyroid tumors." (PMID 39936166, 2025).
toxocariasis (2 papers, 2013 to 2019). A parasitic infection caused by worms found in domestic animals. "The purpose of this study was to determine the role of a Th2-type response induced via STAT6-mediated signaling in the outcome of experimental murine toxocariasis caused by the L2 of the nematode T. canis." (PMID 23509764, 2013). "Our data demonstrate that Th2-type response induced via STAT6-signaling pathway mediates susceptibility in toxocariasis." (PMID 23509764, 2013). "To better understand the possible roles played by M1 and M2 macrophages during acute toxocariasis, we used STAT1- or STAT6-deficient mice." (PMID 31810203, 2019). "Using STAT6−/− BALB/c mice, we have analyzed the role of STAT6-induced Th2 response in determining the outcome of experimental toxocariasis caused by embryonated eggs of the helminth parasite Toxocara canis." (PMID 23509764, 2013). "Collectively, these data suggest that STAT6 deficiency promotes M1 macrophage activation and lung tissue damage, while the absence of STAT1 is associated with M2 macrophage polarization and early lung tissue repair during acute toxocariasis." (PMID 31810203, 2019).
tuberculosis (2 papers, 2020 to 2024). A chronic, recurrent infection caused by the bacterium Mycobacterium tuberculosis. "We showed that the triggering of signal transducer and activator of transcription 6 (STAT6) in interleukin (IL)-4-activated human macrophages (M(IL-4)) prevents FM formation induced by pleural effusion from patients with tuberculosis." (PMID 33002063, 2020).
Type 1 Diabetes (2 papers, 2012 to 2019). "Selective loss of STAT6 may contribute to beta cell demise during the progression of type 1 diabetes." (PMID 30338340, 2019). "Importantly, analysis of human pancreas sections revealed that STAT6 is markedly depleted in the beta cells of individuals with type 1 diabetes, implying the loss of cytoprotective responses." (PMID 30338340, 2019). "Given that this then enhances the propensity of the cells to resist the effects of cytotoxic insults, these results suggest that decreases in STAT6 and SIRPα could contribute to beta cell demise during the progression of type 1 diabetes in susceptible individuals." (PMID 30338340, 2019). "Moreover, we reveal that the expression of STAT6 is significantly diminished in the beta cells of individuals with type 1 diabetes and propose that this is likely to enhance their susceptibility to the actions of proinflammatory cytokines during disease progression." (PMID 30338340, 2019). "Both proteins are well described as anti-apoptotic molecules in the context of the beta cell and the present data demonstrating a loss of STAT6 from beta cells in type 1 diabetes implies that anti-apoptotic responses could be downregulated under these conditions." (PMID 30338340, 2019). "Immunofluorescence analysis revealed a similar pattern, with STAT6 robustly expressed in ICIs from healthy individuals but diminished in the islets of individuals with type 1 diabetes." (PMID 30338340, 2019). "As previously reported, HLA class I (HLAI) expression was significantly elevated in ICIs with depleted STAT6 expression from subjects with type 1 diabetes." (PMID 30338340, 2019). "As expected, STAT6 was expressed robustly within the islets of control individuals but it was noticeably reduced in the insulin-containing islets (ICIs) of people with type 1 diabetes." (PMID 30338340, 2019). "Measurements of the MFI of the anti-STAT6 immunolabelling confirmed the downregulation of STAT6 in ICIs in type 1 diabetes." (PMID 30338340, 2019). "Despite this evidence, the mechanisms involved in promoting beta cell viability in response to STAT6 activation are unclear and it is not known whether this pathway is altered during the autoimmune attack associated with type 1 diabetes." (PMID 30338340, 2019).
vaginal infection (2 papers, 2021 to 2022). "The mechanisms of the effects of vaginal infections induced by E. coli on pregnancy outcome revealed that macrophages located at the maternal-foetal interface might have a crucial effect and further affect pregnancy outcomes through the IL-4/JAK-1/STAT-6 signalling pathway." (PMID 35090514, 2022).
abortion (1 paper, 2022). the ending of pregnancy by removing a fetus or embryo before it can survive outside the uterus. "The LPS-induced mouse model of abortion is a suitable in vivo model for future investigation of the role of the SEC5/STAT6 molecular pathway in M2 polarization of uterine Mφs." (PMID 36313547, 2022).
acute GVHD (1 paper, 2024). "The STAT6-driven Th2 pathway and immune regulatory cytokines (IL10, TGFβ) are associated with the regulation of Th1 cytokine IFNγ production and the mitigation of acute GVHD, the severity of which is more dominantly driven by Th1 cytokines." (PMID 39796136, 2024).